NAT2 (N-acetyltransferase 2)
Diseases named in the same sentence as NAT2 in open-access papers (continued):
Sharing a sentence is not in itself a finding about the gene and the disease.
tumor (continued). "In addition, IHC staining displayed lower expression of VDR and NAT2 in tumor tissues than matched normal tissues and simultaneous alteration of the two proteins in 19 cases, among which three typical cases were displayed." (PMID 34867333, 2021). "Consistent with the previous study, we found that the expressions of NAT1 and NAT2 was significantly reduced in tumor tissues at the mRNA and protein levels, possibly attributable to the highly frequent deep deletion of both genes in COAD, which was confirmed by cBioPortal analysis." (PMID 34322151, 2021). "Finally, to haplotype the NAT2 locus in tumor and patient-matched normal samples in a clinical setting, we develop and demonstrate a long-read sequencing based assay." (PMID 33384440, 2020). "As a majority of slow NAT2 primary tumor cell cultures are inhibited by APA, these findings motivate studies determining whether the cohort of targetable patients should include tumors retaining slow acetylator NAT2 variants other than *6 after undergoing LOH." (PMID 32161261, 2020). "Further, a modest, but measurable >30% decrease in the ratio of slow to rapid NAT2 tumor volumes was observed for animals treated with liposomal APA (p < 0.05), meaning that rapid NAT2 tumors on average grew faster than the corresponding slow NAT2 tumor on each animal." (PMID 32161261, 2020). "Following removal of short sequencing reads (< 1500 nt), barcode de-multiplexing and read alignment we observed that mean NAT2 coverage per sample was 1547 × in the normal tissues and 2229 × for the tumor samples, which was deemed sufficient to call the haplotypes." (PMID 33384440, 2020). "Compared to the immune infiltrate levels of six cells, deletion of NAT1 and NAT2 was associated with substantially lower levels of four immune cell types, including B cells, CD8+ T cells, neutrophils, and dendritic cells, which indicated their influence on the tumor microenvironment." (PMID 34322151, 2021). "Moreover, database analysis and our experimental results showed that NAT2 was substantially downregulated in CRC and negatively correlated with the AJCC stage, which indicates that NAT2 may act as a tumor suppressor gene in CRC." (PMID 34867333, 2021). "Above results we noticed that IL4R, IL2RB and NAT2, which were differentially expressed in CRC tumor, significantly affect both pathological stages and prognosis of CRC patients, collectively." (PMID 35698180, 2022). "The expression of SLC27A2, SFRP2, KRT17 were up-regulated in tumor tissues (p<0.05), the expression of TAGLN was down-regulated (p<0.05), while those of NAT2 remained unchanged (p>0.05), compared with the levels in the corresponding normal tissues." (PMID 36479114, 2022). "After confirming that NAT2 haplotype resolution is feasible by SMRT sequencing, we aimed to resolve the genotype of 74 CRC tumor and patient-matched normal tissues, which included the Swedish cohort." (PMID 33384440, 2020). "We developed SMRT sequencing of NAT2 as a practical diagnostic technology, assigning the genetic variation found in the NAT2 locus to each DNA strand of the individual and potentially allowing the identification of LOH events in the patient’s tumor." (PMID 33384440, 2020). "We sequenced the barcoded NAT2 amplicons from the normal tissues in two separate SMRT cells with 37 samples each, whereas the patient-matched tumor samples were sequenced in three additional SMRT cells with ~ 25 samples each, aiming for better tumor coverage." (PMID 33384440, 2020). "Therefore, it is speculated that the drugs xanthohumol and dapsone may affect tumor progression by affecting the abnormally expression of LCAT and NAT2, respectively." (PMID 36353119, 2022).
infection (1 paper, 2025). The state of being infected such as from the introduction of a foreign agent such as serum, vaccine, antigenic substance or organism. "Transcript levels of some of the key DMEs were upregulated in the liver of the infected mice, 8 weeks post-infection like Nat2, Cyp2e1, Slco1b2, Ces1, Ces2, and Aadac (upregulated by almost 2–3-fold)." (PMID 41358489, 2025).
psychiatric disorder (1 paper, 2020). A disorder characterized by behavioral and/or psychological abnormalities, often accompanied by physical symptoms. "This may be linked to existing evidence of the involvement of specific polymorphisms of genes, such as CYP2D6, NAT2, and PON1, both in cellular detoxification and pathophysiology of psychiatric disorders and MCS, although further studies on these aspects are needed." (PMID 32916833, 2020).
NAT2 also shares sentences with these, for which no sentence is quoted: type 2 diabetes (4 papers); acute myeloid leukemia (2); Cancers of the liver (2); laryngeal carcinoma (2); oral cancer (2); pancreatic cancer (2); peripheral neuropathy (2); acute respiratory distress syndrome (1); adenocarcinoma (1); age-related macular degeneration (1); AIDS-associated diseases (1); alcoholism (1); atopic asthma (1); Azoospermia (1); bladder (1); breast tumor (1); cancer of the exocrine pancreas (1); candidiasis (1); cataract (1); chronic hepatitis B (1); chronic kidney failure (1); chronic lung disease (1); Chronic Myeloid Leukemia (1); Cirrhosis (1); co-infection (1); coronary artery disease (1); coronary atherosclerosis (1); cryptogenic cirrhosis (1); Encephalopathy (1); end-stage renal disease (1).
A further 29 diseases each share a sentence with NAT2 in 1 paper.